ENSG00000200294
Synonyms: LOC124902572
Gene: Small nucleolar RNA gene on chromosome 10 (72,180,858 to 72,180,989, forward strand). Ensembl gene ENSG00000200294.
Gene Ontology:
Biological process: RNA processing
Cellular component: nucleolus
Homologues: Orthologues: mouse Gm25520 (55% identical), mouse Gm23613 (50% identical). Paralogues in human: SNORA36C (83% identical), SNORA36A (83% identical), SNORA36B (74% identical).